IGFBP1 (insulin like growth factor binding protein 1)
Diseases named in the same sentence as IGFBP1 in open-access papers (continued):
Sharing a sentence is not in itself a finding about the gene and the disease.
cardiovascular disease (18 papers, 2013 to 2025). "This study differs from previous work on IGFBP-1 and cardiovascular disease because of the novelty of applying IGFBP-1 to MACE risk prediction in PAD patients specifically, which has not been undertaken previously." (PMID 40710778, 2025). "Multiple studies have demonstrated associations between IGFBP-1 and various forms of cardiovascular disease." (PMID 40710778, 2025). "Studies described in the preceding section showed that circulating IGFBP-1 concentrations were inversely associated with markers of cardiovascular disease." (PMID 39595651, 2024). "Cross-sectional and prospective studies demonstrate associations between IGFBP-1 and cardiovascular diseases." (PMID 39595651, 2024). "There are associations between IGFBP-1 and cardiovascular diseases, however the evidence that IGFBP-1, alone, is a good biomarker is not strong." (PMID 39595651, 2024). "In this study we investigated the association of plasma IGFBPs (IGFBP-1, 3 and 7) with weight, central adiposity and cardiovascular disease markers Hs-CRP and Ox-LDL." (PMID 34394011, 2021). "As described in the literature, the IGF-binding protein-1 (IGFBP-1) is also associated with cardiovascular disease." (PMID 28609475, 2017). "While we found a correlation to all-cause mortality, it is worth noting that the incidence of cardiovascular disease was higher in the groups with elevated PTH levels and highest in the group with elevated levels of PTH and high levels of IGFBP-1 (60%)." (PMID 39592711, 2024). "Some prospective longitudinal cohort studies report that higher fasting serum IGFBP-1 levels predict higher cardiovascular disease mortality." (PMID 39595651, 2024). "The groups with elevated PTH levels had higher incidence and the group with elevated levels of PTH and high levels of IGFBP-1 had the highest incidence of cardiovascular disease." (PMID 39592711, 2024). "Particular attention should be paid to controlling for the influence of these factors in future studies of IGFBP-1 and cardiovascular diseases." (PMID 39595651, 2024). "While lower circulating IGFBP-1 concentrations are associated with an unfavorable cardiometabolic risk profile, higher IGFBP-1 predicts worse cardiovascular disease outcomes." (PMID 39595651, 2024). "Furthermore, most patients enrolled in studies of IGFBP-1 related to cardiovascular disease are male." (PMID 40710778, 2025). "Previous study has associated large vessel diseases with IGFBP-1 abnormalities, suggesting that IGFBP-1 might be a critical factor in the cardiovascular disease pathophysiology." (PMID 38157252, 2023). "In the Framingham population study (n = 3523, mean 62 y, 53% F) over nearly 30 years, higher IGFBP-1, IGFBP-2 and IGF-I predicted cardiovascular disease mortality." (PMID 39595651, 2024). "We next investigated if loss of IGFBP-1 influences vascular function, recognizing that several studies report a negative correlation between IGFBP-1 and biomarkers of cardiovascular disease such as blood pressure, BMI, waist/hip ratio, and fasting insulin levels." (PMID 32190801, 2020).
infection (7 papers, 2015 to 2025). The state of being infected such as from the introduction of a foreign agent such as serum, vaccine, antigenic substance or organism. "From bioinformatic analysis, we identified three significant genes (GCG, APOA1, and IGFBP1) associated with the infection of H. pylori, and the survival nomogram based on the H. pylori-related genes exhibited good predictive power for survival outcome among GC subjects." (PMID 37846989, 2023). "As expected, infection with MAX-overexpression siRNA resistance lentivirus rescued the decreased IGFBP1 level on MAX knockdown." (PMID 35146559, 2022). "As expected, infection with OSR2-overexpression lentivirus, rather than control virus, at least partly rescued the downregulated IGFBP1 expression level upon MAX knockdown." (PMID 35146559, 2022).
metabolic disorders (7 papers, 2013 to 2025). "Although persuasive in supporting the argument that low levels of IGFBP-1 serve as a driver for the development of metabolic disorders, such studies cannot prove a causal role for IGFBP-1." (PMID 32190801, 2020). "When there is an excess of growth hormone or metabolic disorders, levels of IGFBP1 decrease, potentially resulting in severe physiological phenomena such as abdominal spasms, gastrointestinal bloat, and diarrhea." (PMID 40052788, 2025). "Women's health; Pregnancy; Metabolism; Metabolic disorder; Nutrition; Obstetrics & gynecology; IGFBP-1, Insulin, Lipids, MMP-8." (PMID 32923723, 2020). "Of note, abnormal expression of other IGFBP such as IGFBP-1 and IGFBP-2 was detected in different states of metabolic disorders where reduced serum levels of both proteins were associated with cardiovascular risk factors." (PMID 24340035, 2013). "Thus it highlights the possible use of IGFBP-1 as a screening marker for metabolic disorders." (PMID 34394011, 2021).
digestive system tumours (3 papers, 2014 to 2022). "Decreased nuclear WTAP in NASH leads to the impairment of the WTAP/HDAC1 axis and increases the transcription of Igfbp1, Cd36 and Ccl2, which further increases lipolysis in WAT, hepatic FFA uptake and liver inflammation, respectively, finally causing NASH pathogenesis." (PMID 35927268, 2022).
retinopathy (2 papers, 2020 to 2021). "The mRNA expression profile at P17 was comparable to the expression at P12, with more than a 2-fold decrease of Igf1 and Igfbp3 in the hyperglycemic oxygen-induced retinopathy versus normoglycemic oxygen-induced retinopathy groups (both < 0.0001); Igfbp1 mRNA expression was the same in each group." (PMID 33004691, 2020).
endocrine disorders (1 paper, 2023). "IF diets may also benefit metabolic and endocrine disorders in PCOS by changing the circulating levels of Insulin-like Growth Factor-1 (IGF-1) and Insulin-like Growth Factor-Binding Protein 1 (IGFBP1)." (PMID 37242145, 2023).
neurodegenerative disease (1 paper, 2025). A disorder of the central nervous system characterized by gradual and progressive loss of neural tissue and neurologic function. "In our present study, four m6A feature regulators (YTHDC1, IGFBP1, IGF2BP1, and ALKBH5), critically implicated in psychiatric disorders and neurodegenerative diseases, were identified to be associated with PTSD." (PMID 41149057, 2025).
IGFBP1 also shares sentences with these, for which no sentence is quoted: bladder cancer (5 papers); androgen excess (4); Cirrhosis (3); heart disease (3); cervical carcinoma (2); Clear Cell Renal Cell Carcinoma (2); endometrial tumor (2); non-small cell lung carcinoma (2); Prader-Willi syndrome (2); rheumatoid arthritis (2); acanthosis nigricans (1); adenomyosis (1); age (1); alcohol dependence (1); amyloidosis (1); anemia (1); anorexia nervosa (1); Anxiety (1); Arthritis (1); autoimmune disease (1); benign tumors (1); bladder tumors (1); bone metastasis (1); brain injury (1); breast adenocarcinoma (1); breast tumors (1); cerebral palsy (1); cerebrovascular disease (1); cholestasis (1); complication (1).
A further 47 diseases each share a sentence with IGFBP1 in 1 paper.